TAF11L5 (TATA-box binding protein associated factor 11 like 5)
Gene: Protein-coding gene on chromosome 5 (17,525,235 to 17,525,831, forward strand). Ensembl gene ENSG00000284234.
Gene Ontology:
Molecular function: RNA polymerase II general transcription initiation factor activity; protein heterodimerization activity
Biological process: RNA polymerase II preinitiation complex assembly; transcription initiation at RNA polymerase II promoter
Cellular component: transcription factor TFIID complex; nucleus
Homologues: Orthologues: tropical clawed frog taf11 (45% identical), zebrafish taf11 (45% identical), Drosophila melanogaster Taf11 (42% identical), Caenorhabditis elegans taf-11.1 (33% identical), Caenorhabditis elegans taf-11.2 (27% identical). Paralogues in human: TAF11L10 (100% identical), TAF11L6 (100% identical), TAF11L7 (100% identical), TAF11L8 (100% identical), TAF11L3 (99% identical), TAF11L4 (99% identical), TAF11L9 (99% identical), TAF11L13 (95% identical), TAF11L2 (92% identical), LINC02218 (88% identical), TAF11L12 (87% identical), TAF11L11 (85% identical), and 2 more.